SETDB1 (SET domain bifurcated histone lysine methyltransferase 1)
Diseases named in the same sentence as SETDB1 in open-access papers (continued):
Sharing a sentence is not in itself a finding about the gene and the disease.
pancreatic cancer (3 papers, 2022 to 2024). "While there is no SETDB1-specific methyltransferase inhibitor available, these preclinical studies suggest that it might be a therapeutic target of cancer immunotherapy for pancreatic cancer." (PMID 36048239, 2022).
Prader-Willi syndrome (3 papers, 2020 to 2021). "However, H3K9me3 levels throughout the Prader-Willi syndrome (PWS) locus encompassing SNRPN, were similar between WT and ATF7IP-KO or SETDB1-KO." (PMID 34795250, 2021).
pulmonary fibrosis (3 papers, 2023 to 2026). Chronic progressive interstitial lung disorder characterized by the replacement of the lung tissue by connective tissue, leading to progressive dyspnea, respiratory failure, or right heart failure. "SETDB1 has been shown to regulate the TGFβ response in cancer and in T cells and pulmonary fibrosis contexts." (PMID 38691608, 2024). "In a pulmonary fibrosis model, SET domain bifurcated 1 (SETDB1) indirectly induced E‐cadherin expression by increasing H3K9me3 abundance at the Snail promoter, which in turn enhanced TGF‐β‐induced ferroptosis." (PMID 37229485, 2023). "Conversely, SETDB1 can oppose TGF-β–induced EMT by repressing SNAI1, as reported in breast epithelial cells and pulmonary fibrosis models." (PMID 41493679, 2026). "SETDB1 has also been shown to be a regulator of the TGFβ/SMAD pathway in cancer and pulmonary fibrosis contexts." (PMID 38691608, 2024).
triple-negative breast carcinoma (3 papers, 2022 to 2024). An invasive breast carcinoma which is negative for expression of estrogen receptor (ER), progesterone receptor (PR), and human epidermal growth factor receptor 2 (HER2). "Correlative expression of LINC00115, methylation PLK3, SETDB1, and HIF1α are prognostic for clinical triple-negative breast cancers." (PMID 38520019, 2024). "Further, analyses using TCGA data bases showed that SETDB1 is highly expressed in ER+ and triple negative breast cancer (TNBC) compared to normal breast." (PMID 35395812, 2022). "In fact, SETDB1 is amplified in triple negative breast cancers (TNBC) and is shown to regulate TNBC metastasis by enhancing stem-cell-like properties and modulating the epithelial-mesenchymal transition (EMT) program." (PMID 35395812, 2022).
Anxiety (2 papers, 2021). Intense feelings of nervousness, tension, or panic often arise in response to interpersonal stresses. "Such anxiety or stereotypical behavior in Setdb1mGFAPCKO mice implies that the role of Setdb1 in other nerve cells needs to be further studied." (PMID 34026436, 2021). "In line with the role of SETDB1 as risk factor for several NDDs in humans, mice lacking KAP1, a crucial binding partner of SETDB1, displayed a significant anxiety phenotype accompanied by learning and memory deficits." (PMID 34803599, 2021).
Autoimmunity (2 papers, 2020 to 2021). The occurrence of an immune reaction against the organism's own cells or tissues. "In addition, overexpressed SETDB1 also regulates the transcription of genes related to the host innate immune response, apoptosis, tumour growth and autoimmunity to inhibit growth and autoimmunity in ADCs and SCCs." (PMID 34299035, 2021).
brain inflammation (2 papers, 2022 to 2026). "Their transcription is regulated by TRIM28 and SETDB1, which are involved in the regulation of epigenetic processes, in neural cell differentiation, and brain inflammation." (PMID 42123339, 2026). "HERV activation is regulated by TRIM28 and SETDB1, which are part of the epigenetic mechanisms that organize the chromatin architecture in response to external stimuli and are involved in neural cell differentiation and brain inflammation." (PMID 35682642, 2022).
endometrial carcinoma (2 papers, 2022). A malignant tumor arising from the epithelium that lines the cavity of the uterine body. "Additionally, the SETDB1 mutation frequency in patients with mixed endometrial carcinomas was the highest (15.09% of 517 cases), including 8.51% (44 cases) mutation and 6.58% (34 cases) amplification." (PMID 35656340, 2022). "The Human Protein Atlas and our preliminary data demonstrated that high expression of APH1A, GDH2, SETDB1, and SOX9 are associated with low survival in endometrial cancer." (PMID 36230806, 2022). "SETDB1, a histone lysine 9 methyltransferase, is markedly increased in various tumors, including ovarian, breast, lung, and endometrial cancer." (PMID 36230806, 2022).
germ cell tumor (2 papers, 2018 to 2022). A benign or malignant, gonadal or extragonadal neoplasm that originates from germ cells. "We first confirmed that the loss of SETDB1 and its binding partner WDE specifically in germ cells was the cause of the germ cell tumor phenotype." (PMID 30297796, 2018). "Because of the known connection between the germ cell tumor phenotype and ectopic testis gene transcription, we wondered whether SETDB1 played a role in silencing the expression of testis genes in female germ cells." (PMID 30297796, 2018). "The results showed that SETDB1 expression was significantly related to clinicopathological stages of tumors, including PAAD (p = 0.0444), LIHC (p = 0.0132), KICH (p = 0.00939), and testicular germ cell tumors (TGCT) (p = 0.0468)." (PMID 35656340, 2022).
Hepatic steatosis (2 papers, 2020 to 2025). Steatosis is a term used to denote lipid accumulation within hepatocytes. "In this process, upregulated miR-216b-5p binds to the 3'UTR of Setdb1 mRNA and interferes with its mRNA stability, which in turn exacerbates hepatic steatosis." (PMID 40130250, 2025).
Multiple Myeloma (2 papers, 2022). "As SETDB1 mRNA levels were strikingly upregulated in multiple myeloma, we would like to explore the potential mechanisms underlying this phenomenon." (PMID 35372573, 2022). "To further determine the molecular mechanisms underlying protumorigenic effect of SETDB1 in myeloma cells, we firstly performed differential gene expression analysis between the SETDB1high (N = 106) and SETDB1low (N = 106) groups from GSE136337." (PMID 35372573, 2022). "Between the two groups, SETDB1 expression was linked with clinical parameters like myeloma isotype and cytogenetic abnormalities (p < 0.05, Chi-squared test)." (PMID 35372573, 2022). "Here, increased SETDB1 expression was observed in the plasma cells from newly diagnosed multiple myeloma patients compared to those from the normal controls." (PMID 35372573, 2022). "Multivariate cox regression analysis was also performed to assess the predictive value of SETDB1, and these findings indicated that high SETDB1 expression in multiple myeloma was an independent unfavorable prognostic factor for OS and EFS (p < 0.05)." (PMID 35372573, 2022). "The result showed that there were substantial differences of SETDB1 expression between multiple myeloma cells (MMCs) and normal plasma cells (NPCs) (p < 0.01, Wilcoxon test)." (PMID 35372573, 2022). "In conclusion, these data suggested high expression of SETDB1 was an adverse prognosis factor in multiple myeloma." (PMID 35372573, 2022). "We made further validation of the reproducibility and accuracy of SETDB1 expression in the prognostic impact of myeloma patients by analyzing two additional independent and large sample datasets, consisting of MMRF-CoMMpass and GSE136337." (PMID 35372573, 2022). "SETDB1 high expression myeloma cells exhibited increased expression of those cell cycle-related genes." (PMID 35372573, 2022). "We have demonstrated that increased SETDB1 gene copy numbers contributed significantly to the aberrant SETDB1 expression and high SETDB1 expression was an unfavorable prognostic biomarker in myeloma patients." (PMID 35372573, 2022). "Firstly, we calculated the mRNA expression of SETDB1 of plasma cells from the healthy controls (HC, n = 6) and newly diagnosed myeloma patients (NDMM, n = 170) in GSE39754 database." (PMID 35372573, 2022). "Functional enrichment analysis suggested that SETDB1 could promote cell cycle progression in myeloma." (PMID 35372573, 2022). "In our analysis, SETDB1 expression levels were significantly upregulated in myeloma samples." (PMID 35372573, 2022). "Our study firstly revealed the prognostic function of SETDB1 expression in multiple myeloma." (PMID 35372573, 2022). "Hence, it has been demonstrated that SETDB1 may regulate the cell cycle genes leading to disease progression in multiple myeloma." (PMID 35372573, 2022). "Besides, the relationship between SETDB1 expression and its prognostic values in multiple myeloma has not been studied." (PMID 35372573, 2022).
Obesity (2 papers, 2019 to 2022). Accumulation of substantial excess body fat. "Among the genes, GABARAPL2 is associated with total and high‐density lipoprotein–cholesterol, and SETDB1 is an antiadipogenic factor playing a role in obesity." (PMID 35386394, 2022). "Moreover, SETDB1 and TRIM28 (also known as KAP1), which both repress retrotransposons, also modulate obesity in mice." (PMID 31877125, 2019).
Rett syndrome (2 papers, 2021 to 2023). A severe neurodevelopmental disorder affecting the central nervous system.
thyroid carcinoma (2 papers, 2018 to 2022). "Further annotation revealed that genes nearby H4K20me3/H3K4me3 marks are bound by OCT4, SETDB1, and SIN3B, are involved in DNA methylation, imprinting, gametogenesis, and sex determination, and are associated with thyroid carcinoma." (PMID 29969988, 2018).
acute monocytic leukemia (1 paper, 2024). Acute monoblastic leukemia (AML-M5), is one of the most common subtypes of acute myeloid leukemia (AML) that is either comprised of more than 80% of monoblasts (AML-M5a) or 30-80% monoblasts with (pro)monocytic differentiation (AML-M5b). "Arsenic trioxide (As2O3) has been reported to severely reduce SETDB1 levels by inducing promyelocytic leukemia protein degradation (R, R)-59 is a selective SETDB1-TTD small molecule inhibitor screened based on this concept that has been shown to inhibit SETDB1 in acute monocytic leukemia cells." (PMID 39583200, 2024).
acute promyelocytic leukemia (1 paper, 2021). An aggressive form of acute myeloid leukemia (AML), characterized by arrest of leukocyte differentiation at the promyelocyte stage, due to a specific chromosomal translocation t(15;17) in myeloid cells. "Regarding Acute Promyelocytic Leukemia (APL), an aggressive subtype of AML, SETDB1 is a stable member and responsible for the integrity of PML-NBs which are found interspersed in chromatin, regulating transcription, apoptosis and DNA damage responses." (PMID 34440561, 2021).
Allergy (1 paper, 2022). An allergy is an immune response or reaction to substances that are usually not harmful. "Therefore, environmental factors responsible for the increasing number of subjects affected by allergy could exert their actions via TRIM28/SETDB1‐ and/or HERV‐driven variations in targeted biologic processes." (PMID 35344298, 2022). "Despite the potential impact of HERVs and of TRIM28 and SETDB1 in triggering and/or maintaining allergic reactions, to the best of our knowledge no studies explored their expressions in allergic patients." (PMID 35344298, 2022).
amyotrophic lateral sclerosis (1 paper, 2021). Amyotrophic lateral sclerosis (ALS) is a neurodegenerative disease characterized by progressive muscular paralysis reflecting degeneration of motor neurons in the primary motor cortex, corticospinal tracts, brainstem and spinal cord. "Lastly, neurodegeneration and memory deficits in Frontotemporal Dementia (FTD) and Amyotrophic Lateral Sclerosis (ALS) are linked to a global downregulation of the H3K9me3 mark, further demonstrating the implication of SETDB1 in the pathogenesis of neuropsychiatric diseases." (PMID 34440561, 2021).
asthma (1 paper, 2023). "rs139189121, rs75406390, and rs59024312 are genic upstream transcript variants located between exon 3 and exon 4 of SETDB1, which could influence SETDB1 expression activity and transcription of the SETDB1 protein, resulting in a different asthma prognosis." (PMID 37569643, 2023). "We identified two potentially novel (SETDB1 and ZNF8) and five previously reported (DM4C, DOCK8, MMP20, MYL7, and ADCY9) genes associated with increased asthma risk." (PMID 37569643, 2023). "Using follow-up bioinformatics analyses, we also confirmed that two novel genes (SETDB1 and ZNF8) and three previously reported genes (DOCK8, MMP20, and ADCY9) are potential asthma-associated genes." (PMID 37569643, 2023). "This study demonstrated that two potentially novel genes (SETDB1 and ZNF8) are associated with the development of asthma, based on gene–smoking interaction analyses using multiple cohorts of the KoGES consortium." (PMID 37569643, 2023). "In addition, SETDB1 interacts with the asthma-related gene SETDB2; the latter antagonizes the KDM4C gene to control H3K9 methylation, which affects the expression of ORMDL3, a well-known asthma-related gene." (PMID 37569643, 2023). "Therefore, further biological investigation is needed to elucidate whether rs139189121, rs75406390, and rs59024312 can affect the expression of SETDB1 and asthma prognosis." (PMID 37569643, 2023).
astrocytic tumor (1 paper, 2015). A glial tumor of the brain or spinal cord showing astrocytic differentiation. "A novel finding is that H3K9me3 levels increased in parallel with those of SETDB1 consistent with the notion that this histone mark is preferentially established by SETDB1 rather than by SUV39H1 in astrocytic tumors." (PMID 25602259, 2015).
B-cell lymphomas (1 paper, 2024). "Primary mouse embryonic fibroblasts (PMEF) derived from Suvar39h double knockout (dn) mice and B-cell lymphomas formed in Suvar39h dn mice show a polyploid DNA content, and mouse oocytes devoid of SETDB1 show misaligned chromosomes and multiple spindles." (PMID 38831123, 2024). "Primary mouse embryonic fibroblasts (PMEF) derived from Suvar39h dn mice and B-cell lymphomas formed in Suvar39h dn mice show a polyploid DNA content, whereas mice oocytes devoid of SETDB1 show misaligned chromosomes and multiple spindles." (PMID 38831123, 2024).
chronic hepatitis (1 paper, 2020). An active inflammatory process affecting the liver for more than six months. "Interestingly, in this study the authors found that the median SETDB1 protein levels increase progressively along the continuum from normal liver to chronic hepatitis to HCC, suggesting a role for SETDB1 in the oncogenesis of HCC." (PMID 33050946, 2020).
Cockayne syndrome (1 paper, 2021). A multisystem condition characterized by short stature, a characteristic facial appearance, premature aging, photosensitivity, progressive neurological dysfunction, and intellectual deficit. "This suggests that CSB defects in Cockayne syndrome are strongly related to SETDB1 downregulation and Heterochromatin loss, allowing for PAR buildup from freely-transcribed regions and thus, mitochondrial dysfunction from freely-transcribed regions and, finally, mitochondrial dysfunction." (PMID 34440561, 2021).
COVID-19 (1 paper, 2021). A disease caused by infection with severe acute respiratory syndrome coronavirus 2. "Positive correlations emerged between the transcriptional levels of type I and II IFNs, TRIM28, SETDB1, and HERVs in COVID-19 patients." (PMID 34299101, 2021). "Briefly, our findings suggest that aberrant expressions of TRIM28 and SETDB1 in COVID-19 children may condition the evolution of the infection via their crucial regulatory functions on the immune system, from the innate response to the adaptive response." (PMID 34299101, 2021). "The significant positive correlations between transcripts of IFN-I and IFN-II and of TRIM28 and SETDB1 suggest that the former may exert important regulatory functions on the transactivation of the latter in COVID-19 children." (PMID 34299101, 2021). "Despite the potential mutual interplays between TRIM28/SETDB1, HERVs, and SARS-CoV-2, no investigations have explored their activation in patients affected by COVID-19, but a recent report that has highlighted the higher expression of MSRV-env in adults." (PMID 34299101, 2021).
Ewing sarcoma (1 paper, 2024). A small round cell tumor that lacks morphologic, immunohistochemical, and electron microscopic evidence of neuroectodermal differentiation. "Of the priority candidates, 6 were found with enriched dependency in Ewing Sarcoma cell lines (AKT1, BARD1, HSP90AA1, NCOA1, SETDB1, SMAD4)." (PMID 38177639, 2024).
food allergy (1 paper, 2022). Gastrointestinal disturbances, skin eruptions, or shock due to allergic reactions to allergens in food. "Given the influence of HERVs and of TRIM28 and SETDB1 on innate and adaptive immune responses, their transcriptional activation in children with food allergies suggest that they might play important roles in the development of these diseases." (PMID 35344298, 2022).
HIV-1 infection (1 paper, 2018). The type species of lentivirus and the etiologic agent of acquired immunodeficiency syndrome (AIDS). "The SETDB1 protein is a histone H3 methyltranferase that, in the context of HIV-1 infection, interacts with and also methylates Tat, and its knockdown in vitro produces an increase in viral transactivation." (PMID 29449904, 2018).
ileitis (1 paper, 2023). "A number of genetic studies reveal that mice with genetic ablation of Caspase-8, Fas associated via death domain (Fadd), or SET domain bifurcated histone lysine methyltransferase 1 (Setdb1) in IECs develop spontaneous ileitis and colitis owing to sensitizing cells to RIPK3-mediated necroptosis." (PMID 36795486, 2023).
latent infection (1 paper, 2020). "KAP1, which coordinates chromatin-remodeling proteins such as Mi2α, SETDB1, and HP1, recruits the H3K9 methyltransferase, SETDB1, resulting in the deposition of repressive H3K9me3 histone marks at the MIE enhancer/promoter during latent infection." (PMID 33113934, 2020).
Lupus (1 paper, 2026). "Lupus patients showed reduced TRIM28 and increased SETDB1 expression, consistent with altered regulation of HERV repression pathways." (PMID 41828687, 2026).
lymph node metastasis (1 paper, 2020). "However, the expression of SETDB1 was not related to the clinical characteristic of CRC, including age, gender, location, pathological differentiation, depth of tumor, lymph node metastasis, distant metastasis, and tumor stage." (PMID 32393761, 2020).
male infertility (1 paper, 2020). The inability of the male to effect fertilization of an ovum after a specified period of unprotected intercourse. "This study will provide a new perspective on SETDB1 function and understanding of male infertility." (PMID 33133132, 2020).
myeloid leukemia (1 paper, 2025). A clonal proliferation of myeloid cells and their precursors in the bone marrow, peripheral blood, and spleen. "In contrast, myeloid leukemia cells significantly downregulate LINE-1 expression via SETDB1-mediated H3K9 trimethylation, likely preventing activation of the interferon pathway." (PMID 41010280, 2025).
neuroblastoma (1 paper, 2021). Neuroblastoma (NB) is the most common solid, extracranial childhood tumor. "Neither expression of SETDB1 nor SUV39H1/SUV39H2 could be associated with the increased telomeric H3K9me3 in ALT-positive neuroblastomas." (PMID 33627664, 2021).